UBE2G1 (ubiquitin conjugating enzyme E2 G1)
Description:
Accepts ubiquitin from the E1 complex and catalyzes its covalent attachment to other proteins. In vitro catalyzes 'Lys-48'-, as well as 'Lys-63'-linked polyubiquitination. May be involved in degradation of muscle-specific proteins. Mediates polyubiquitination of CYP3A4.
Synonyms: UBE2G; UBC7; E217K
Tractability: PROTAC: UniProt records ubiquitination sites on it; ubiquitination databases record sites on it; its protein half-life has been measured.
Gene: Protein-coding gene on chromosome 17 (4,269,259 to 4,366,675, reverse strand). Ensembl gene ENSG00000132388.
Subcellular location (Human Protein Atlas): Cytosol; Nucleoplasm
Pathways (Reactome):
Immune System: Antigen processing: Ubiquitination & Proteasome degradation
Metabolism of proteins: Synthesis of active ubiquitin: roles of E1 and E2 enzymes
Gene Ontology:
Molecular function: protein binding; ubiquitin conjugating enzyme activity; ubiquitin protein ligase binding; ubiquitin-protein transferase activity; ubiquitin-like protein transferase activity
Biological process: protein K48-linked ubiquitination; protein K63-linked ubiquitination; proteasome-mediated ubiquitin-dependent protein catabolic process; protein polyubiquitination; ubiquitin-dependent protein catabolic process; protein ubiquitination
Cellular component: extracellular exosome; cytosol
Genetic constraint (gnomAD): Loss-of-function variants: 5 observed, 17.48 expected, observed/expected ratio (o/e) 0.29, 90% interval 0.15 to 0.6. The upper end of that interval is the gene's LOEUF score, 0.6, which puts it in group 2 of 6, group 1 being the genes least tolerant of losing a copy. Missense variants: 88 observed, 196.31 expected, observed/expected ratio (o/e) 0.45, 90% interval 0.38 to 0.54. Synonymous variants: 73 observed, 62.15 expected, observed/expected ratio (o/e) 1.17, 90% interval 0.97 to 1.43.
Homologues: Orthologues: chimpanzee UBE2G1 (100% identical), dog UBE2G1 (100% identical), mouse Ube2g1 (100% identical), rabbit UBE2G1 (100% identical), tropical clawed frog ube2g1 (99% identical), zebrafish ube2g1a (99% identical), pig UBE2G1 (98% identical), rat Ube2g1 (97% identical), macaque UBE2G1 (94% identical), guinea pig UBE2G1 (91% identical), rat Ube2g1l1 (86% identical), Drosophila melanogaster CG40045 (82% identical), and 2 more. Paralogues in human: CDC34 (54% identical), UBE2R2 (53% identical), UBE2G2 (50% identical), UBE2I (32% identical), UBE2N (31% identical), UBE2U (31% identical), UBE2F (29% identical), UBE2C (29% identical), UBE2T (29% identical), UBE2K (28% identical), UBE2A (28% identical), UBE2B (28% identical), and 12 more.
Diseases named in the same sentence as UBE2G1 in open-access papers:
UBE2G1 is named in the same sentence as 13 diseases in open-access papers, as found by Europe PMC text mining. Sharing a sentence is not in itself a finding about the gene and the disease. The quoted sentences say what the papers report.
multiple myeloma (2 papers, 2018 to 2022). "UBE2G1-deficient OPM2 myeloma cells are resistant to lenalidomide and pomalidomide but remain sensitive to CC-220 at clinical relevant concentrations." (PMID 30234487, 2018). "UBE2G1 loss also reduced the degradation of GSPT1 induced by CC-885 in myeloma cell lines OPM2, DF15 and MM1S, AML cell lines OCI-AML2, U937, MOLM-13 and MV4-11, as well as 293T human embryonic kidney cells." (PMID 30234487, 2018). "UBE2G1-deficient myeloma cells, however, remained sensitive to a more potent IKZF1/3 degrader CC-220." (PMID 30234487, 2018). "UBE2G1 loss confers resistance to lenalidomide and pomalidomide in myeloma cell lines." (PMID 30234487, 2018). "Although loss of UBE2G1 conferred resistance to LEN and POM in human myeloma cell lines, it remains to be seen whether UBE2G1 deficiency occurs in human myeloma patients with inherent or acquired resistance to IMiD drug treatment, especially those with normal cereblon expression." (PMID 30234487, 2018). "For example, UBE2G1 inactivation significantly attenuated the degradation of myeloma survival factors IKZF1 and IKZF3 induced by lenalidomide and pomalidomide, hence conferring drug resistance." (PMID 30234487, 2018). "To test this hypothesis, we surveyed the protein expression level of UBE2G1 in myeloma cell lines with variable sensitivity to LEN and POM." (PMID 30234487, 2018). "As observed in screens for lenalidomide resistance in multiple myeloma, CC-885 requires the components of the CRL4CRBN ubiquitin ligase, genes required for neddylation of cullin-RING ligases, and the UBE2G1 E2 ubiquitin–conjugating enzyme." (PMID 35763353, 2022). "Ablation of UBE2G1 significantly diminished the degradation of IKFZ1, IKZF3 and ZFP91 by LEN, POM, and CC-220, as well as CK1α degradation by LEN in OPM2, DF15 and MM1S myeloma cells." (PMID 30234487, 2018). "Yet, myeloma cells that did not have UBE2G1 and were resistant to certain drugs could still respond to other more potent drugs." (PMID 30234487, 2018).
Alzheimer disease (1 paper, 2023). A progressive, neurodegenerative disease characterized by loss of function and death of nerve cells in several areas of the brain leading to loss of cognitive function such as memory and language. "Ubiquitin Conjugating Enzyme E2 G1 (UBE2G1) transcripts in the blood could be used as biomarkers of Alzheimer’s disease." (PMID 38328521, 2023).
Cognitive impairment (1 paper, 2021). Abnormal cognition is characterized by deficits in thinking, reasoning, or remembering. "Striated Muscle Enriched Protein Kinase (SPEG) and UBE2L3 that may be structurally and functionally related to Ubiquitin Conjugating Enzyme E2 G1 (UBE2G1) were differentially methylated genes associated with cognitive impairment and circulating UBE2G1 transcripts may have potential as biomarkers." (PMID 34182925, 2021).
muscular atrophy (1 paper, 2017). The loss of muscle tissue due to inactivity or disease. "By contrast, UBE2R (CDC34) and UBE2G1 protein levels were upregulated after denervation, and these E2 enzymes could potentially modulate the function of E3 ligases during muscular atrophy." (PMID 28546288, 2017).
soft tissue tumors (1 paper, 2022). "Another point we should address is that MYH9::USP6 was first identified in MO, and the novel USP6 fusion partners UBE2G1 and SNHG3 were uncovered in one case with MO and one case with FO, respectively, expanding our knowledge of USP6-associated soft tissue tumors with bone metaplasia." (PMID 36727055, 2022).
UBE2G1 also shares sentences with these, for which no sentence is quoted: cancer (2 papers); tumor (2); gastric carcinoma (1); Huntington disease (1); infection (1); osteoarthritis (1); Parkinson disease (1); spinocerebellar ataxia (1).